Y_RNA (Y RNA )
Gene: Miscellaneous RNA gene on chromosome 9 (110,934,406 to 110,934,507, forward strand). Ensembl gene ENSG00000207401.
Homologues: Orthologues: chimpanzee Y_RNA (100% identical), macaque Y_RNA (96% identical). Paralogues in human: Y_RNA (87% identical), RNY3 (86% identical), Y_RNA (86% identical), RNY3P1 (85% identical), Y_RNA (85% identical), RNY3P11 (84% identical), RNY3P14 (84% identical), Y_RNA (84% identical), Y_RNA (83% identical), RNY3P10 (82% identical), Y_RNA (82% identical), RNY3P3 (81% identical), and 94 more.